Y_RNA (Y RNA )
Gene: Miscellaneous RNA gene on chromosome 12 (50,743,568 to 50,743,684, forward strand). Ensembl gene ENSG00000200428.
Homologues: Orthologues: chimpanzee Y_RNA (99% identical), macaque Y_RNA (91% identical). Paralogues in human: Y_RNA (80% identical), RNY1 (79% identical), Y_RNA (79% identical), Y_RNA (78% identical), RNY1P11 (77% identical), RNY1P7 (77% identical), Y_RNA (77% identical), Y_RNA (76% identical), Y_RNA (75% identical), RNY1P8 (74% identical), Y_RNA (74% identical), RNY1P10 (74% identical), and 92 more.